HLA-E (major histocompatibility complex, class I, E)
Diseases named in the same sentence as HLA-E in open-access papers (continued):
Sharing a sentence is not in itself a finding about the gene and the disease.
cancer (continued). "High circulating levels of sHLA-E were also found in various cancer settings, which led to the development of a novel immune check point inhibitor targeting the HLA-E specific NKG2A inhibitor receptor, namely Monalizumab." (PMID 35806227, 2022). "In this review, we summarise and discuss the various strategies currently in development which either directly or indirectly disrupt the NKG2A:HLA-E interaction to enhance NK cell activation against cancer." (PMID 36560403, 2022). "Therapeutic strategies aimed at disrupting the NKG2A:HLA-E axis therefore have high potential for overcoming cancer mediated immune suppression in various solid and haematological cancer settings." (PMID 36560403, 2022). "Our data reveals that selinexor, in addition to its direct cytotoxic activity, also activates an anti-cancer immune response via disruption of the inhibitory NKG2A:HLA-E axis." (PMID 34926302, 2021). "Taken together, these observations provide a strong rationale for the use of anti-NKG2A-blocking monoclonal antibodies to improve the efficacy of donor-derived NK cells against HLA-E-positive cancers." (PMID 34071607, 2021). "A related non-classical HLA molecule commonly overexpressed on the surface of various cancers is HLA-E." (PMID 34201079, 2021). "Our data identifies that the selective XPO1 inhibitor selinexor disrupts the inhibitory NKG2A:HLA-E axis to activate NK cells against cancer." (PMID 34926302, 2021). "Experimental evidence suggests important contributions of HLA-G and HLA-E to immune escape in many cancers." (PMID 34201079, 2021). "Even though intra-tumoral NKG2A+ve NK cells are seen in the tumor microenvironment, the upregulation of HLA-E by cancer cells implies that these NK cells are functionally exhausted." (PMID 33304346, 2020). "In turn, the overexpression of HLA-E on cancer cells drives the upregulation of CD94/NKG2A on cytotoxic lymphocytes, including NK cells, in both hematological and solid tumors." (PMID 33255582, 2020). "In human cancer, while classical HLA alleles are frequently lost to prevent T-cell recognition, HLA-E expression is even upregulated, as a protective mechanism of cancer cells against immune surveillance and elimination by cytotoxic lymphocytes." (PMID 33255582, 2020). "High levels of HLA-E have been reported in several cancer types, including NSCLC, glioblastoma, melanoma, breast (BC), liver, kidney, gynecological, and colorectal cancers." (PMID 33255582, 2020). "Recent approaches targeting specifically MIC proteins, NKG2DLs and HLA-E or their receptors to avoid the immunosuppressive action of these MHC molecules in cancer are currently under investigations." (PMID 32887413, 2020). "In contrast to MHC class Ia molecules, HLA-E are highly upregulated on cancer cells and APCs in the cancer microenvironment." (PMID 32451453, 2020). "When NKG2A expression was lost, these cells showed higher cytotoxicity toward HLA-E positive cancer cells." (PMID 33304346, 2020). "Whereas knowledge of the role of HLA-F in cancer is sparse, HLA-E expression is also seen in several cases of cancers associated with immune suppression." (PMID 32560316, 2020). "An imminent need is recognized to generate anti-HLA-E mAbs that can bind only to amino acid sequences (epitopes) unique or specific for HLA-E and to revalidate the expression of HLA-E on the cell surface of cancer cells." (PMID 31009335, 2019). "In contrast, HLA-E is upregulated in several cancers, including HNC, CxCa, breast, rectal, colon, and ovarian cancers." (PMID 28623356, 2017). "MICA and HLA-E have key functions in the immune responses against cancer, infection and allogeneic solid organ transplant." (PMID 27907087, 2016). "Additionally, several soluble factors associated with the senescence phenotype were highly expressed in HLA-E positive cancer cells, particularly GDF15, MMP2, and MMP7." (PMID 40959273, 2025).
cancer (continued). "Moreover, HLA-E-positive cancer cells interacted with mesothelial cells via various cell-matrix proteins, including collagen and TNC (sFigure 6B)." (PMID 40959273, 2025). "Moreover, our results indicated that HLA-E-expressing senescent cancer cells have greater immunomodulatory effects on immune cells compared to HLA-E-negative cancer cells." (PMID 40959273, 2025). "Similarly, cancer cells also influenced all CD8 T cell clusters through the expression of HLA-E (sFigure 6A)." (PMID 40959273, 2025). "We identified several key molecular mechanisms, including the role of senescent cancer cell-expressed HLA-E in impairing NK cell cytotoxicity and reducing the recruitment of cDC1, leading to a diminished population of this critical antigen-presenting cell subset." (PMID 40959273, 2025). "As such, the inhibitory NKG2A:HLA-E axis may be modulated by XPO1 inhibition via two mechanisms within the TME: downregulating HLA-E on cancer cells and dampening IL-10 production." (PMID 40291981, 2025). "HLA-E has been proven to participate in the immune evasion mechanism of cancer cells." (PMID 40959273, 2025). "Therefore, the immunoregulatory effects of HLA-E and HLA-G overexpression on cancer prognosis require further investigation." (PMID 41463341, 2025). "High NKG2A expression could be exploited by HLA-E-expressing cancer cells, enabling them to evade NK immune surveillance." (PMID 40211394, 2025). "It interacts with its ligand, HLA-E, which is often expressed on the surface of cancer cells." (PMID 38256137, 2024). "HLA-F and HLA-E negatively coexpressed with LINC01614 in more than six cancers." (PMID 38655053, 2024). "In vitro cytotoxicity assays demonstrated that BRY805 effectively activated NK92 cells and primary NK cells, thereby enhancing the cytotoxic activity of effector cells against cancer cells overexpressing HLA-E, with significantly greater efficacy compared to monalizumab." (PMID 39584993, 2024). "In addition to the suppression of T-cells, our data on the expression of ULBP2 and HLA-E shows that inhibition of NK cells also drives progression from precancer to cancer." (PMID 39672307, 2024). "The immune evasive role of HLA-E/NKG2A immune checkpoint is confirmed in a variety of cancers." (PMID 39867897, 2024). "Notably, the favorable prognostic effect of infiltrating CTLs in EOC was neutralized by high expression of HLA-E on the surface of the cancer cells, suggesting that HLA-E impedes antitumoral CTL activity in the TME." (PMID 38067396, 2023). "To establish the proof‐of‐concept that this strategy may work in cancer patients, we performed experiments on xenografted human HLA‐E+ tumors implanted in immunodeficient mice." (PMID 37782273, 2023). "It has been reported that NKG2A and HLA-E are upregulated in various cancer cells." (PMID 38041084, 2023). "Our strategy enabled high and stable levels of HLA-E expressed on the surface of all cancer cell lines, whereas HLA-E level could be cell-line dependent upon exposure to IFN-γ." (PMID 37675109, 2023). "Their results also imply that blockade of HLA-E:CD94-NKG2A may be a potential approach for cancer treatment." (PMID 38041084, 2023). "Vascular cells and cancer cells express high level of HLA-E presenting self peptides from HLA Ia leader peptides, and thus may be targeted by HLA-EUL40 CD8 T cells due to peptide sequence mimicry." (PMID 36980230, 2023). "However, the clinical use of customized NKG2A+ or NKG2A− Vδ2 T cells should be matched with the histopathologic features of HLA-E expression to tailor those immunotherapeutic protocols to exert the most powerful immune responses against cancers." (PMID 36831606, 2023). "Using HLA-E (Face-2) polyreactive antibodies may lead to errors in interpreting the results of immunodiagnosis of HLA-E on tissues and cancer cells." (PMID 35214796, 2022). "Interestingly, HLA-E ligation of NKG2A can be used to improve cancer therapeutics in certain settings." (PMID 36560403, 2022).
cancer (continued). "In addition, various cytotoxic anti-cancer agents can unleash the activity of NKG2A+ NK cells which are highly sensitive to small changes in surface HLA-E expression on target cells." (PMID 36560403, 2022). "HLA‐E has been shown to present peptides in response to cellular stress, and has more recently been shown to play a role in regulating immunity in the cancer setting." (PMID 35108401, 2022). "Natural killer group 2A (NKG2A) is an inhibitory checkpoint receptor that binds human leukocyte antigen-E (HLA-E) expressed on cancer cells, which could lead to the elimination of cancer cells by NKG2A-positive NK cells." (PMID 35958612, 2022). "The high proportion of NK cells that express NKG2A, which increases further after transplantation or ex vivo expansion, and the upregulation of HLA-E in certain tumors, emphasize the need to develop strategies to overcome inhibition of NK cells for use in cancer immunotherapy." (PMID 35585985, 2022). "Moreover, the researcher evaluated the combination of the NKG2A antibody monalizumab and anti-EGFR antibody cetuximab in treating patients with squamous cell carcinoma of the head and neck, a type of cancer with strong expression of HLA-E." (PMID 34439285, 2021). "Thus, HLA-G and HLA-E are consistent features of EwS and are responsive to inflammatory stimuli in this cancer." (PMID 34201079, 2021). "We conclude that non-classical HLA molecules are expressed in EwS under inflammatory conditions, but have limited functional impact on antigen-specific T cells, arguing against a relevant therapeutic benefit from combining CART therapy with HLA-G or HLA-E checkpoint blockade in this cancer." (PMID 34201079, 2021). "Therefore, identification of effector cells against HLA-E+ tumors would help advance therapeutic strategy against these most malignant tumors." (PMID 33968044, 2021). "And diselenide bonds could be broke to form selenic acid under γ-radiation, which can inhibit HLA-E protein expression, ultimately up-regulating cancer immunity of NK cells." (PMID 32408880, 2020). "The prognostic value of HLA-E has been verified in various of cancers." (PMID 32066399, 2020). "Moreover, different open discussion papers are available about the role, for example, of HLA-E in co-cultures of cancer cells and PBMCs." (PMID 33096896, 2020). "Moreover, future experiments exploring the effect of PPAPs on cancer cells with dysregulated levels of HLA-E, MICA/B and MHC are also needed." (PMID 32887413, 2020). "Human leukocyte antigen E (HLA-E) was expressed on the membranes of several types of cancer cells." (PMID 32408880, 2020). "Therefore, a humanized or human monospecific anti-HLA-E mAb mimicking TFL-033 is bound to be a valuable agent for passive immunotherapy of human cancers." (PMID 31009335, 2019). "Taken together, these data indicate that, although some malignancies do not seem to correlate with a presence of any of the HLA-E alleles, the substantial number of cancer diseases is associated with HLA-EG (*01:03) allele." (PMID 31690066, 2019). "In contrast to classical HLA molecules which are frequently lost, HLA-E protein levels are generally increased in cancer when compared to their healthy counterparts, as described in lung, kidney, pancreas, stomach, colon, head and neck, liver, melanoma, prostate, and rectal tumor tissues." (PMID 31623687, 2019). "The expression and function of HLA-E in cancer cells is not fully understood, but it may represent a mechanism of tolerance that could be influenced by HLA-E polymorphism." (PMID 26261988, 2015). "Membrane and soluble HLA-E molecules can also contribute to cancer immune escape by their interaction with the inhibitory receptor NKG2A on NK and T cells; their immunosuppressive activity yet unknown is likely." (PMID 24204708, 2013). "For example, up-regulation of HLA-E is considered a potential marker for cancer." (PMID 21679443, 2011).
cancer (continued). "Moreover, NKG2A blockade can promote expanded NK cell cytotoxicity against HLA-E+ cancer cells." (PMID 40291981, 2025). "For instance, antibody-drug conjugates (ADCs) tailored to target precise TAAs bound to HLA-E could capitalize on rapid intracellular internalization, enabling highly effective delivery of potent cytotoxic agents directly into cancer cells, thereby acting as “biological missile”." (PMID 39301027, 2024). "Notably, we observed that the interaction between HLA-E and NKG2A (either alone or in a complex with CD94), which is associated with T cell inhibition and increased cancer growth, was enriched in CXCL13+ CD8+ TRMs interacting with epithelial cells at CC tissues." (PMID 39014148, 2024). "Indeed, 3D12 was also used for monitoring the cell surface distribution of HLA-E on human cancers." (PMID 38390869, 2024). "Importantly, high expression of HLA‐E is related to poorer prognosis in cancer patients." (PMID 35596615, 2022). "We demonstrate that cancer-derived blebbisomes contain a plethora of inhibitory immune checkpoint proteins, including PD-L1, PD-L2, B7-H3, VISTA, PVR and HLA-E." (PMID 39984653, 2025). "Although numerically modest, PTSPs were recurrent across samples and included products from cancer/immune genes (e.g., MITF, DAPK1, HLA-E), with synthetic-peptide validation and evidence of immunogenicity." (PMID 41293269, 2025). "Given the critical role of the HLA-E/NKG2A axis in immune evasion by both HCMV and cancers, novel therapeutic approaches are being developed to target this pathway." (PMID 41463341, 2025). "ITF3756 also affect the gene expression level of HLA-E (the non-classical human leukocyte antigen-E), an antigen constitutively expressed on nucleated cells at low levels but reported to be overexpressed in multiple solid tumors and associated with worse clinical outcome in different cancers." (PMID 40433358, 2025). "We found that cancer-cell-derived blebbisomes express not only PD-L1 but also a plethora of other inhibitory ligands, including PD-L2, B7-H3 (CD276), VISTA (B7-H5), HLA-E, PVR (CD155) and Nectin-2 (CD112)." (PMID 39984653, 2025). "Overexpression of HLA-E results in inhibition of NK-cell-mediated cytotoxicity via the NKG2A/CD94 receptor and provides a mechanism for viruses (such as HCMV) and cancers to evade immune clearance." (PMID 41463341, 2025). "Upon incubation with these cancer cells, NK92 cells demonstrated minimal cytotoxic activity, attributed to the interaction between HLA-E and NKG2A/CD94, which subsequently inhibited NK92 cell cytotoxicity." (PMID 39584993, 2024). "In most of the cancers, there was a significant correlation between UBE2C gene expression and HLA‐DMB, HLA‐DOA, HLA‐DPA1, HLA‐PDB1, HLA‐DRA, and HLA‐E." (PMID 38577722, 2024). "Meanwhile, the highly expression of HLA-E as a ligand for KLRC1, KLRK1, and NKG2A/CD94 on the surface of NK cells can help cancer cells evade immune killing by NK cells." (PMID 39583114, 2024). "Among these, PLXNA3, HLA-E, DDX58, IKBKE, HSPA6, SOS2, and HSPA1A stood out, with significantly elevated expression levels in LIHC compared to other cancer types." (PMID 39000042, 2024). "To achieve a comprehensive and objective evaluation of MHC-I expression in cancers, we developed a MHC-I signature score based on GSVA of eight MHC-I family genes, including HLA-A, HLA-B, HLA-C, HLA-D, HLA-E, HLA-F, HLA-H, and B2M." (PMID 39408874, 2024). "Thus, HLA-E expression in cancer tissues may be regulated by TME." (PMID 38007483, 2023). "In specific, TIS is referred to as an 18‐gene signature (CCL5, GZMK, CD3D, CD3E, CD2, HLA‐DRA, IL2RG, NKG7, CIITA, CXCR6, LAG3, TAGAP, HLA‐E, CXCL13, IDO1, CXCL10, STAT1, and GZMB), which was related to the response to ICIs in various cancers." (PMID 37434432, 2023). "Some of these genes such as HLA-E and HLA-C are directly related to MHC-I signaling by the cancer cell." (PMID 36230778, 2022).
cancer (continued). "HLA-E and HLA-G are ligands for NKG2A and LIR, respectively, and cancer cells upregulate the expression of these MHC-I molecules to avoid killing by NK cells." (PMID 34439285, 2021). "We additionally identified as positive biomarkers several interactions between MHC-I genes and the corresponding receptors (HLA-B_HLA-E → KLRD1 and HLA-E → KLRC1 in 17 and 14 cancer types, respectively)." (PMID 34430923, 2021). "Using polyreactive anti-HLA-E mAbs, enumerable studies suggest overexpression of HLE-E on the cell surface of several human cancers." (PMID 31009335, 2019). "By surveying HLA-E levels on target cells, the CD94/NKG2 complex is thought to detect general downregulation of HLA complexes by viruses or cancer." (PMID 29898768, 2018). "This antibody therapy blocks the inhibition signal of the NKG2A receptor, and thereby unleashes those cells towards cancer cells, which can express high levels of the NKG2A ligand HLA-E." (PMID 28008151, 2017). "Given that HLA-E is heavily influenced by cytokines and other signals, it will be important to dissect the immunogenic properties of XPO1 inhibition in other models of human cancers which recapitulate the TME in patients." (PMID 40291981, 2025). "We find that cancer cells release blebbisomes containing an abundance of immune evasion and inhibitory immune checkpoint proteins, including PD-L1, PD-L2, B7-H3, VISTA, PVR, Nectin-2, HLA-E, CD73 and CD47." (PMID 39984653, 2025). "This represents a highly promising anti-cancer strategy, which theoretically could also potentially be repurposed to target HCMV-infected cells that overexpress HLA-E, thereby redirecting immune responses toward viral clearance rather than inhibition." (PMID 41463341, 2025). "Complementary approaches could also focus on γδ T cells, especially in MMRd cancers with MHCI defects 47, DCs 29,48, PD-1 and PI3K-γ expressing myeloid cells 49,50, the HLA-E and HLA-G molecules 20,35,51–56, WRN inhibitors 57 or TREM1 myeloid cells." (PMID 40027748, 2025). "NKG2A forms a heterodimer with CD94 and recognizes self-peptide bound to non-classical MHC-I molecule, HLA-E, which is widely expressed in different cancer types." (PMID 40948803, 2025). "Inhibition of HLA-E expression through RNA interference enhanced NK cell-mediated cytotoxicity against SnCs suggesting the usage of monalizumab, a therapeutic antibody targeting NKG2A, in cancer patients." (PMID 38561826, 2024). "However, the introduction of BRY805 disrupted the binding between HLA-E and NKG2A/CD94, thereby enabling NK92 cells to effectively target and kill the cancer cells." (PMID 39584993, 2024). "The existence of non-classical HLA-I (HLA-Ib: HLA-E, F, G, and H) has gained great interest due to its particular role in the modulation of the immune response to cancer." (PMID 39766165, 2024). "HLA-E is a nonclassical HLA class I molecule that has been shown in many studies to benefit cancer progression via immune escape." (PMID 39329751, 2024). "In recent years, non-classical HLAs—including HLA-E, HLA-F, HLA-G, and HLA-H—have emerged as critical players in the immune landscape of cancer due to their diverse and less conventional functions in immune modulation." (PMID 39766165, 2024). "Noncanonical peptides display higher sequence heterogeneity as compared to classical HLA-leader-derived peptides presented by HLA-E, can be recognized by specific T cells through their TCR, and have been identified in the context of various infectious diseases and potentially cancers." (PMID 38691588, 2024). "Human leukocyte antigen-E (HLA-E) is a non-classical MHC molecule whose overexpression in several human cancer types has been reported." (PMID 38007483, 2023). "Although HLA-E expression on the cancer cell surface is increased in response to IFN-γ in the TME, in our study, we transduced all solid tumor cell lines with HLA-E plus HLA-Cw1502 signal peptide to overcome the low expression of HLA-E on in vitro cultured cells." (PMID 37675109, 2023).